S1PR2 (sphingosine-1-phosphate receptor 2)
Diseases named in the same sentence as S1PR2 in open-access papers (continued):
Sharing a sentence is not in itself a finding about the gene and the disease.
cancer (continued). "Therefore, S1PR2 can play multiple functions in the progression of cancer by affecting a diverse range of downstream second messengers." (PMID 31807117, 2019). "Little is known of its role in cancer and somatic mutations have not been observed in the 44 tissues sequenced for S1PR2 in the COSMIC database." (PMID 21781349, 2011). "Notably, in esophageal adenocarcinoma (EAC) cells, TCA was shown to promote invasive growth, epithelial-mesenchymal transition (EMT), and cancer stem cell expansion specifically through S1PR2 activation, a process involving downstream YAP and β-catenin signaling pathways." (PMID 40821794, 2025). "S1PR2 is expressed on various cell types relevant to the TIME, including myeloid cells (macrophages, monocytes, neutrophils) and certain cancer cells, positioning it to potentially influence tumor-associated inflammation and progression." (PMID 40821794, 2025). "ACER3 is associated with the AKT/BAX pathway and activates the S1P phosphorylation of AKT through S1PR2 and PI3K in cancer cells." (PMID 32498325, 2020). "In summary, S1PR2 adds another layer of complexity to BA signaling within the TIME, potentially acting as a receptor for conjugated BAs to influence cancer cell invasiveness and inflammation, possibly contributing to a pro-tumorigenic microenvironment in certain settings." (PMID 40821794, 2025). "Several other modulators, such as the dual inhibitors of SPHK1 and SPHK2, N,N-dimethylsphingosine (DMS) and SKI-II, the SPHK2 antagonist opaganib (ABC294640), the S1PR1 and S1PR3 antagonist VPC23019, and the S1PR2 agonist CYM5520, have been extensively utilized in cancer treatment and research." (PMID 39519028, 2024). "The function of S1PR2 in cancer is uncertain, because both positive and negative impacts of S1PR2 were reported by different studies." (PMID 32887262, 2020). "Thus, a cancer promoting role was suggested for S1PR1 and S1PR3 subtypes, while S1PR2 presence demonstrated potential growth-limiting effects." (PMID 29385066, 2018). "The migration of several cancer cells was promoted by S1PR1/3, but prevented by S1PR2." (PMID 29385066, 2018). "Of note and although S1PR2 functions in cancer are still obscure, our data suggest that S1P/S1PR2 signaling in MC may promote local VEGF production and therefore angiogenesis, potentially linking inflammation to cancer." (PMID 26884643, 2016). "However, the modulation of S1PR2 did not impact the migratory properties of RKO cancer cells, thus indicating that the migration capacities of these cells are S1PR2-independent." (PMID 33225975, 2020). "Similarly, SPNS2 has been shown to deliver S1P to S1PR2, leading to increased epidermal growth factor (EGF)-mediated cancer cell invasion, suggesting that SPNS2 inhibitors may be useful therapeutics for cancer treatment." (PMID 35565311, 2022). "Studies on SPHK1 inhibitors have made some progress, while no ideal SPHK1 inhibitor is currently used for treating cancer in the clinic, and there are also other compounds including S1PR1 and S1PR3 (VPC03090) or S1PR2 (AB1) antagonists under preclinical evaluation." (PMID 36361531, 2022).
infection (12 papers, 2016 to 2025). The state of being infected such as from the introduction of a foreign agent such as serum, vaccine, antigenic substance or organism. "S1P in turn was exported out of cells and activated S1PR2, whose expression was increased during infection." (PMID 38033162, 2023). "Transcriptomic analysis of purified splenic B cells demonstrated reduced expression of genes encoding critical adhesion and co-stimulation molecules, including GC-adhesion gene S1PR2, at severe stages of infection." (PMID 37146079, 2023). "We primed AID-Confetti or S1pr2-Tomato mice by intranasal infection and fate-mapped activated B cells by tamoxifen administration at 7, 10, and 13 days post-infection, covering the initial period of GC formation." (PMID 31866068, 2020). "Three days after lentiviral infection, the S1PR2 shRNA reduced the S1PR2 mRNA level by an average of 63.9% compared with control shRNA treatment." (PMID 30609675, 2019). "Concurrently, infection led to increased expression of the S1PR2." (PMID 38033162, 2023). "It would be interesting to investigate whether the infection of other GC-specific Cre strains such as AID-Cre or S1pr2-Cre results in an equal deletion efficiency after immunization and infection." (PMID 38132100, 2023). "Together, these results suggest that the downregulation of genes associated with adhesion molecules, especially genes encoding the critical receptors S1PR2 and GPR183, may contribute to the loss of GCs and disrupt of B/T cell interaction at the severe stage of infection." (PMID 37146079, 2023). "B cell transcriptomics indicated significant downregulation of several adhesion molecules during infection, including S1PR1, S1PR2, ITGA4, ITGA6, GPR183, and CCR7." (PMID 37146079, 2023). "We found that N. meningitidis induces S1P release from brain endothelial cells in parallel with increased expression of S1PR2 and downstream activation of the epidermal growth factor receptor, indicating a shift in the S1PR signalling balance during infection." (PMID 38033162, 2023). "JTE-013 treatment was sufficient to inhibit N. meningitidis MC58 uptake by hCMEC/D3 until 6h but not 8h infection, possibly due to increasing expression of S1PR2." (PMID 38033162, 2023). "Although p-PI3K was significantly suppressed by treatment with S1PR2 shRNA in murine BMSCs regardless of Aa infection, the S1PR2 shRNA significantly enhanced p-Akt in uninfected cells and increased p-Akt in Aa infected cells." (PMID 36834810, 2023). "In addition, TGR5, S1PR2, and VDR were the main BARs that have been affected by the infection." (PMID 39287458, 2024). "We observed a reduction in p-Smad3 in murine BMSCs treated with JTE013 or the S1PR2 shRNA and infected with Aa compared to JTE013 or the S1PR2 shRNA-treated BMSCs without Aa infection." (PMID 36834810, 2023). "Besides, compared to the control group without infection, the protein levels of CK19 increased after C. sinensis infection (P<0.01), however, inhibition of S1PR2 can significantly decrease the CK19 expression compared to the C. sinensis-infected group (P<0.05)." (PMID 36339341, 2022).
bacterial infection (3 papers, 2019 to 2023). "As the S1P–S1PR2 axis is essential to maintaining the skin barrier and protecting the skin from bacterial infection, the skin barrier is impaired in the S1PR2-deleted epidermis." (PMID 37830566, 2023). "Future studies will need to determine if S1PR2 can co-localize with TLR4, MyD88, RANK, TRAF6, MAPKs, PI3K, Src, and integrins in lipid rafts in response to bacterial infection or RANKL stimulation." (PMID 30609675, 2019). "In summary, the present study is the first to demonstrate that treatment with the S1PR2 antagonist (JTE013) enhanced TGFβ/Smad and Akt signaling and increased VEGFA, PDGFA, and GDF15 gene expressions in murine BMSCs with or without bacterial infection." (PMID 36834810, 2023).
inflammation (3 papers, 2018 to 2021). Aberrant reaction of the microcirculation characterized by movement of fluid and leukocytes from the blood into extravascular tissues. "Together with our data showing that S1PR2 mediated high-level DCA-induced intestinal inflammation, these findings provide a strong basis for pharmaceutical studies to verify the efficacy of S1PR2 antagonists in the treatment of inflammatory diseases, including IBD." (PMID 29854830, 2018).
neurodegenerative disease (3 papers, 2020 to 2024). A disorder of the central nervous system characterized by gradual and progressive loss of neural tissue and neurologic function. "Bile acid signaling via FXR and S1PR2 has been implicated in gene expression in the central nervous system and involvement in several neurodegenerative diseases." (PMID 37367841, 2023). "Prior research has elucidated the substantial involvement of S1pr2 in instigating cerebrovascular permeability and inflammation in neurodegenerative disease." (PMID 39679379, 2024).
metabolic disease (2 papers, 2021 to 2024). A congenital disorder (due to inherited enzyme abnormality) or acquired (due to failure of a metabolically important organ) disorder resulting from an abnormal metabolic process. "Compared to FXR and TGR5, the role of S1PR2 in metabolic disease remains largely unclear." (PMID 34831031, 2021). "More studies are needed in order to develop S1PR2-specific therapy for metabolic disease." (PMID 34831031, 2021).
cardiovascular disorder (1 paper, 2023). A disease involving the cardiovascular system. "S1PR2 expression is increased in VECs where it aggravates vascular permeability upon inflammation; S1PR1 is increased in VSMCs and decreased in vascular reactivity in cardiovascular disorders." (PMID 36907884, 2023).
hematologic malignancies (1 paper, 2025). "Indeed, a number of recently developed small molecule modulators selectively targeting S1PR2 or S1PR3, some with extensive clinical testing, appear well positioned to be deployed to regulate CSC function in the therapy of both hematologic malignancies and solid tumours." (PMID 41253780, 2025).
skeletal diseases (1 paper, 2019). "Inhibition of S1PR2 signaling could be a novel therapeutic strategy for bone loss associated with skeletal diseases." (PMID 30609675, 2019). "Our results suggested that inhibition of S1PR2 by its specific antagonist (JTE013) could be a good strategy to treat bone loss associated with skeletal diseases." (PMID 30609675, 2019).
S1PR2 also shares sentences with these, for which no sentence is quoted: biliary atresia (4 papers); Cholestatic liver disease (3); edema (3); fibrosis (3); myeloma (3); prostate carcinoma (3); retinopathy (3); acute myeloid leukaemia (2); acute myocardial infarction (2); anaplastic thyroid cancer (2); Anxiety (2); atopic dermatitis (2); colorectal (2); follicular lymphoma (2); Glucose intolerance (2); Hearing impairment (2); muscular dystrophy (2); neurologic diseases (2); neuropathy (2); Papillary Thyroid Carcinoma (2); portal hypertension (2); thyroid cancer (2); acute lung injury (1); adenocarcinoma (1); allergic contact dermatitis (1); Alzheimer disease (1); autism (1); bile duct obstruction (1); Bradycardia (1); brain injury (1).
A further 51 diseases each share a sentence with S1PR2 in 1 paper.